ABCA4 (ATP binding cassette subfamily A member 4)
Diseases named in the same sentence as ABCA4 in open-access papers (continued):
Sharing a sentence is not in itself a finding about the gene and the disease.
Stargardt disease (continued). "In Stargardt disease, a relatively common IRD with a prevalence of 1 in 8,000–10,000, ROs derived from patient iPSCs with intronic ABCA4 variants demonstrated splicing defects leading to retinal degeneration." (PMID 39422807, 2025). "ROs derived from patients with Stargardt disease have been targeted for preclinical research on ASO-based medications to alleviate splicing defects in the ABCA4 gene." (PMID 39422807, 2025). "Stargardt disease (STGD1), the most common inherited juvenile macular degeneration, is caused by biallelic mutations in the ABCA4 gene." (PMID 41226778, 2025). "Care needs to be taken when it comes to the pleiotropic effect of genes, since modifications can result in serious adverse effects, particularly when the defect concerns large sets, as in ABCA4 responsible for Stargardt disease among other retinal dystrophies." (PMID 41303269, 2025). "Patient IRD-9, a 14-year-old with a clinical diagnosis of Stargardt disease, was found to be compound heterozygous for c.1609C>T and c.5882G>A in the ABCA4 gene." (PMID 41465088, 2025). "Mutations include ABCA4 and BEST1 genes, which are found in different conditions such as Stargardt disease, Best disease, and also in age-related maculopathies." (PMID 40062075, 2025). "Abca4−/− mice, the classical model for Stargardt disease, accumulate high levels of bisretinoids in the RPE due to impaired clearance of retinaldehyde intermediates, leading to light-induced retinal damage." (PMID 41516080, 2025). "The ABCA4 gene, consisting of 50 exons and specific to photoreceptors, plays a key role in Stargardt disease." (PMID 39860622, 2025). "Stargardt disease (STGD1), the most common retinal dystrophy caused by pathogenic variants of the biallelic ABCA4 gene, results in irreversible vision loss." (PMID 40244202, 2025). "Collectively, these results suggest that ABCA4 base editing can be achieved in target cells of Stargardt disease, but optimization of the vector components is necessary to maximize therapeutic benefit." (PMID 39779923, 2025). "There were 18 patients with ABCA4-related Stargardt disease, among whom 6 exhibited adult onset (mean age of onset: 44.3; 3 females, 50%) and 12 exhibited onsets during childhood or adolescence (mean age of onset: 9.6; 6 females, 50%)." (PMID 40244202, 2025). "For larger genes such as ABCA4 (Stargardt disease) and USH2A (Usher syndrome type 2A), dual-AAV systems have been developed to overcome size limitations, while CRISPR/Cas9-based genome editing has been explored for precise mutation correction." (PMID 40143072, 2025). "Mutations in Bestrophin-1 (BEST1) and Crumbs homolog 1 (CRB1) genes have also been reported in patients with Stargardt’s disease with wildtype ABCA4 gene." (PMID 40725253, 2025). "Two kinds of gene therapy are under clinical trials for Stargardt’s disease, those supplementing wildtype ABCA4, and those aiming to modify the disease by expressing other molecules." (PMID 40725253, 2025). "Historically, a prevalence of 1 in 8000 to 10,000 for Stargardt disease has often been quoted in the literature, based on an empirical estimate before the ABCA4 gene was identified." (PMID 40960229, 2025). "Stargardt disease, also called ABCA4-related retinopathy (ABCA4R), is the most common form of juvenile-onset macular dystrophy and yet lacks an FDA approved treatment." (PMID 40699379, 2025). "One study demonstrated that intravitreal injections of PEGylated-ECO nanoparticle carrying plasmid ABCA4-DNA was shown to be safe and effective in mouse models of Stargardt disease." (PMID 39064263, 2024). "We registered that ABCA4 minigene is of interest to at least two companies (five projects in the preclinical phase) focusing on Stargardt disease (inherited retinal degeneration)." (PMID 38488469, 2024). "The initial trial of ABCA4 delivered by lentiviral vectors for treatment of Stargardt disease has showed promising safety data and the evaluation of efficacy is currently ongoing." (PMID 38500685, 2024).
Stargardt disease (continued). "Stargardt disease (STGD1), due to biallelic variants in the ABCA4 gene, is the most common juvenile macular dystrophy, although late-onset forms are recognized." (PMID 39061682, 2024). "Stargardt disease (STGD1), an inherited macular dystrophy caused by mutations in the ABCA4 gene, typically presents with gradual vision loss." (PMID 39398711, 2024). "Thirty (60%) had RPGR-related retinal dystrophy, nine (18%) had ABCA4-Stargardt disease, five (10%) had KCNV2-related retinal dystrophy, three (6%) had RDH12-related retinal dystrophy, two (4%) had Achromatopsia, and one (2%) had Usher syndrome." (PMID 39641965, 2024). "We present 2 cases in which familial DNA was not available to determine the allelic architecture and thus explain phenotypic differences in ABCA4-related Stargardt disease." (PMID 39264853, 2024). "Stargardt disease (STGD1), associated with biallelic variants in the ABCA4 gene, is the most common heritable macular dystrophy and is currently untreatable." (PMID 39061682, 2024). "The allelic arrangement of disease variants has been shown to be integral in determining the prognosis of particular Mendelian diseases such as ABCA4-related Stargardt disease." (PMID 39264853, 2024). "With regards to correcting mutations in Stargardt disease, Wimmer and colleagues introduced split PE2 plasmids into HEK293 cells containing an ABCA4 mutation to evaluate editing efficiency in vitro." (PMID 39064263, 2024). "In the Abca4−/− mouse model of Stargardt disease, increased RPE cell endocytosis of complement factor C3a resulted in increased mTOR activation." (PMID 38920696, 2024). "Stargardt disease (STGD) is the most common form of inherited juvenile macular dystrophy and is caused by sequence variants in the ABCA4 gene." (PMID 39060921, 2024). "Stargardt disease (STGD1; OMIM #248200) is monogenic inherited retinopathy caused by bi‐allelic mutations in the ABCA4 gene." (PMID 36177499, 2023). "The rod function was low even when compared to double null ABCA4 patients and the patient reported nyctalopia as the presenting symptom, which is unusual for Stargardt disease." (PMID 36833218, 2023). "Case 1a represents a typical phenotype of ABCA4-RD, presenting with adolescent-onset “classical” Stargardt disease with macular atrophy, flecks, and peripapillary sparing." (PMID 38066771, 2023). "Over 15% of probands in a large cohort of more than 1500 inherited retinal degeneration patients present with a clinical diagnosis of Stargardt disease (STGD1), a recessive form of macular dystrophy caused by biallelic variants in the ABCA4 gene." (PMID 37296172, 2023). "Mutations in ABCA4 can cause a wide spectrum of IRD phenotypes, including Stargardt disease, fundus flavimaculatus, bull’s eye maculopathy, CORD, and an RP-like phenotype, among others." (PMID 38066771, 2023). "The study is strengthened by a comparison of the WDR19 phenotype with an equally well documented cohort of patients with ABCA4-Stargardt disease." (PMID 36833218, 2023). "The patients’ phenotype was by and large undistinguishable from ABCA4-Stargardt disease; however, there were some atypical findings, notably the degree of foveal sparing and the relatively severe involvement of rod photoreceptors." (PMID 36833218, 2023). "USH2A was the most frequent gene associated with RP, RDH12 early-onset severe retinal dystrophy, ABCA4 Stargardt disease, PROM1 cone-rod dystrophy, and BEST1 macular dystrophy." (PMID 37217489, 2023). "In many of them, mutations in a single gene can explain most cases, e.g., PAX6 and aniridia ⁠, ABCA4 and Stargardt disease ⁠, or NF1 and Neurofibromatosis type 1 ⁠." (PMID 36881176, 2023). "These associations are true for populations of mostly European descent and suggest trans-modifying events in ABCA4/Stargardt disease by variation in other, unlinked, genes." (PMID 35353811, 2022).
Stargardt disease (continued). "We highlight ABCA4 and USH2A with a CF of ~7% and ~3%, respectively, with the first being responsible of Stargardt disease and the later causing Usher syndrome." (PMID 35955564, 2022). "Coding sequences often exceed the kilobase capacity of an AAV vector, including ABCA4 in the IRD Stargardt disease, which is 6.8 kb." (PMID 36293232, 2022). "Substitution of the corresponding basic Arginine to the hydrophobic Tryptophan in ABCA4 (p.R2077W) is identified in a patient with Stargardt disease." (PMID 35361255, 2022). "Stargardt disease (STGD1), also known as fundus flavimaculatus or ABCA4 retinopathy, is a progressive disorder of the retinal pigment epithelium (RPE) and photoreceptors caused by bi-allelic variants of the ABCA4 gene." (PMID 36555803, 2022). "The resulting ABCA4/Stargardt disease is the most prevalent Mendelian eye disorder, although its underlying clinical heterogeneity, including penetrance of many alleles, are not well-understood." (PMID 35353811, 2022). "In previous studies, all Korean patients with Stargardt disease were heterozygotes for two ABCA4 variants." (PMID 36566289, 2022). "This is reasonable when we correlate the clinical phenotypes; CEP290 is related to LCA, RP1L1 is related to occult macular dystrophy (OMD), ABCA4 is related to Stargardt disease and severe forms of autosomal recessive RP, and CYP4V2 is related to BCD." (PMID 33608557, 2021). "The authors detected UDPs in 0.05–0.2% of these trios, amongst which was a chromosome 1 UPD (ABCA4) in a Stargardt disease case, suggesting minimal contribution to the genetic diagnostic yield." (PMID 33799353, 2021). "Changes in the concentration of these granules in Abca4−/− mice (a model of Stargardt disease) relative to age-matched wild-type (WT) controls were investigated." (PMID 34376700, 2021). "With respect to IDRs, founder deep intronic mutations have been reported in ABCA4 and CEP290 which turned out to be major causes of Stargardt disease and LCA, respectively." (PMID 33670832, 2021). "Stargardt disease (STGD1) and ABCA4 retinopathies (ABCA4R) are caused by pathogenic variants in the ABCA4 gene inherited in an autosomal recessive manner." (PMID 34440414, 2021). "On the contrary, DI variants constitute 2% of unique and 4% of all ABCA4 gene variants implicated in the pathogenesis of another autosomal recessive IRD, Stargardt disease." (PMID 34281261, 2021). "AtRAL di has been reported to be more abundant than A2E in the retinas from Abca4−/−Rdh8−/− mice, a model with features of recessive Stargardt disease." (PMID 34626070, 2021). "In view of the family history of Stargardt macular dystrophy (STGD1) and the BEM phenotype genetic testing for ABCA4 variants was undertaken." (PMID 33836713, 2021). "BPN-14136 dosing in the Abca4-/- mouse model of Stargardt disease significantly inhibited bisretinoid synthesis and normalized dysregulation of the complement system in the retina." (PMID 31978148, 2020). "Analysis of the overall ABCA4 gene expression in patients with Stargardt disease showed a high reduction as compared to healthy controls." (PMID 32413971, 2020). "The results show that ABCA4 mRNA is also expressed in the hair follicles obtained from patients with Stargardt disease, however, this expression was significantly lower than in controls (p = 0.0001 by Mann-Whitney U test)." (PMID 32413971, 2020). "Stargardt disease (STGD1), also often referred to as ABCA4-associated retinopathy, is a progressive disorder of the retina, initially characterized by a loss of central vision." (PMID 32653833, 2020). "In order to analyze the overall expression of the ABCA4 gene expression in patients with Stargardt disease we performed qRT-PCR." (PMID 32413971, 2020). "This approach was also shown to alleviate retinal degeneration in animal models of Leber Congenital Amaurosis (Rd16 mice) and Stargardt disease (Abca4−/− mice)." (PMID 32733204, 2020).
Stargardt disease (continued). "In conclusion, analysis of mRNA from hair follicles appears to be a reliable method to assess the biological consequences of functional changes of the ABCA4 gene in patients with Stargardt disease and possibly other ABCA4 retinopathies." (PMID 32413971, 2020). "Early biomarkers of retinal changes in the affected dogs will facilitate the use of the Abca4 mutant dog as a model for human Stargardt disease." (PMID 32260251, 2020). "These genes are known to cause: X-linked RP (RPGR), autosomal recessive RP (MAK and EYS), autosomal dominant RP (PRPF31), Stargardt disease (ABCA4), and Leber congenital amaurosis (GUCY2D)." (PMID 32000842, 2020). "Environmental light has deleterious effects on the outer retina in human retinopathies, such as ABCA4-related Stargardt’s disease and dry age-related macular degeneration." (PMID 32641711, 2020). "Given the initial diagnosis of atypical Stargardt disease in the female proband at age 5, targeted testing of ABCA4 was conducted." (PMID 31721179, 2020). "After extensive optimization, we have previously shown that an overlapping dual vector system for the treatment of Stargardt disease enabled clearly detectable levels of ABCA4 expression in the photoreceptor outer segments of Abca4−/− mice." (PMID 32724727, 2020). "The development of a colony of these dogs as a model for therapy will have a substantial impact on the treatment of humans with Stargardt disease because mouse Abca4−/− models lack a phenotype." (PMID 32260251, 2020). "This is in agreement with results obtained from different cell types, which also showed a reduction of normally spliced full-length ABCA4 mRNA in fibroblasts of patients with Stargardt disease." (PMID 32413971, 2020). "Full-field electroretinogram (ERG) and best corrected visual acuity (BCVA) measures have been shown to have prognostic value for recessive Stargardt disease (also called “ABCA4-related retinopathy”)." (PMID 32751377, 2020). "To date, only one publication showed the possible application of artificial intelligence in ABCA4-related retinopathy showing automatic cone photoreceptor localization for adaptive optics imaging in Stargardt disease, achromatopsia, and retinitis pigmentosa." (PMID 32751377, 2020). "Mutations in retina-specific ATP-binding cassette transporter 4 (ABCA4) are responsible for over 95% of cases of Stargardt disease (STGD), as well as a minor proportion of retinitis pigmentosa (RP) and cone-rod dystrophy cases (CRD)." (PMID 31766579, 2019). "Retinal oxidative damage, associated with an ATP-binding cassette, sub-family A, member 4, also known as ABCA4 gene mutation, has been implicated as a major underlying mechanism for Stargardt disease/fundus flavimaculatus (STG/FF)." (PMID 31618812, 2019). "While lysosomal enzymes degrade material optimally at acidic pH levels, lysosomal pH is elevated in RPE cells from the ABCA4-/- mouse model of Stargardt’s disease, an early onset retinal degeneration." (PMID 29725296, 2018). "Stargardt disease-1 (STGD1, Mendelian Inheritance in Man [MIM] 248,200) is a progressive autosomal recessive macular degeneration linked to pathogenic mutations in ABCA4 (MIM*601,691)." (PMID 30060493, 2018). "Stargardt’s macular dystrophy (fundus flavimaculatus, SMD, or juvenile macular dystrophy) is mostly caused by mutations in ABCR (ABCA4) or less often, ELOV4 genes, both causing photoreceptor (not RPE) cell death." (PMID 29675776, 2018). "Large genes such as MYO7A (Usher syndrome) and ABCA4 (Stargardt disease) have been approached successfully with lentiviruses in pre-clinical studies and are currently being tested in clinical trials." (PMID 28134823, 2017). "Lack of the ABCA4 protein, a Stargardt disease locus, leads to the accumulation of BMP lipids, known to be elevated in endosomal/lysosomal storage diseases and is associated with impaired late endosomal/lysosomal lipid processing." (PMID 29229934, 2017).
Stargardt disease (continued). "Stargardt disease (STGD), also known as Stargardt macular dystrophy, is one of the most prevalent inherited maculopathy, caused by mutations in the ABCA4 gene." (PMID 28151966, 2017). "Stargardt disease, RP, CORD, age-related macular degeneration, fundus flavimaculatus, and EOSRD have been reported to be caused by variants in ABCA4." (PMID 29186038, 2017). "Recently, a rare combination of mutations in ABCA4 and GRM6, genes whose mutations are associated with more than one form of retinal dystrophies, was reported in a patient with atypical Stargardt disease." (PMID 28912962, 2017). "Another success for pharmacological intervention has been achieved in the double-KO Abca4−/−; Rdh8−/− mouse, a model for rod and cone degeneration, resembling features of Stargardt disease." (PMID 25650393, 2015). "If a specific clinical diagnosis was suspected, direct sequencing of disease-specific genes, that is, ABCA4 for Stargardt disease, was conducted." (PMID 26161267, 2015). "Known candidate genes for Stargardt disease such as “ABCA4” contain many exons and there are hundreds of identified mutations." (PMID 24632595, 2014). "Mutations in RPGR and ABCA4 genes have previously been associated with XLRP and Stargardt Disease, respectively." (PMID 25544989, 2014). "ABCA4 is related with some brain-related diseases including stargardt disease 1, early-onset severe retinal dystrophy and age-related macular degeneration." (PMID 23281790, 2012). "Some mouse models of inherited macular dystrophies, including the Abca4 model of Stargardt disease, reproduce the biochemical features of the human disease but only manifest a very slow photoreceptor degeneration, in contrast to the human disease." (PMID 22110650, 2011). "The family showed an uncommon ABCA4-related phenotype in which affected individuals present with classic juvenile Stargardt disease, but rapidly progress to show a severe cone-rod dystrophy clinical phenotype." (PMID 19352439, 2009). "The photoreceptor cell-specific ATP-binding cassette transporter (ABCA4) gene was identified in 1997 and found to be mutated in patients with Stargardt's macular dystrophy." (PMID 17327825, 2007). "A recent study in a Chinese cohort of patients with Stargardt’s disease has shown that 45% of patients with no variants in exon region have deep intronic variants in the ABCA4 gene." (PMID 40725253, 2025). "Thus, we investigated the effect of the Rbp1 gene inactivation on the phenotype of the Abca4−/−/Rdh8−/− model of Stargardt disease." (PMID 40749832, 2025). "Mutations in ABCA4 and BEST1 genes were found in Stargardt disease (STGD)." (PMID 40062075, 2025). "It is a heritable disorder and the ABCA4 gene, expressed at high levels in the rod photoreceptors and encoding ATP-binding cassette (ABC) transporter, has been identified as the causal gene for Stargardt’s disease and shows an autosomal recessive inheritance." (PMID 40725253, 2025). "Similarly to our cohort, studies from Saudi Arabia and the UAE consistently identify ABCA4 as a major IRD gene, with variants such as c.5882G>A strongly linked to Stargardt disease and cone-rod dystrophy." (PMID 41465088, 2025). "Despite the quantum of research on Stargardt’s disease, particularly the extensive studies on the disease associated variants present in the ABCA4 gene, an approved therapy for this disease is lacking and promising therapy remains elusive." (PMID 40725253, 2025). "Finally, using dual AAV injections, PTS mediated by single split inteins has been successfully validated for mid-size proteins such as ABCA4 and factor F8, respectively, in Stargardt disease and hemophilia animal models." (PMID 40493400, 2025). "Stargardt disease (STGD), the leading cause of inherited childhood blindness, is primarily caused by mutations in the ABCA4 gene; yet, the underlying mechanisms of photoreceptor degeneration remain elusive, partly due to limitations in existing animal disease models." (PMID 39610324, 2025).